CFTR (CF transmembrane conductance regulator)
Diseases named in the same sentence as CFTR in open-access papers (continued):
Sharing a sentence is not in itself a finding about the gene and the disease.
respiratory failure (16 papers, 2013 to 2025). The significant impairment of gas exchange within the lungs resulting in hypoxia, hypercarbia, or both, to the extent that organ tissue perfusion is severely compromised. "Dysfunctional CFTR disrupts mucociliary clearance, particularly in the respiratory tract, resulting in persistent bacterial colonization, chronic inflammation, and progressive pulmonary damage—ultimately leading to respiratory failure, the principal cause of mortality in CF patients." (PMID 40732035, 2025). "This pathology is characterized by genetic defects of cystic fibrosis transmembrane conductance regulator (CFTR) gene and recurrent pulmonary infection, which cause chronic inflammation of airways and respiratory failure." (PMID 33672477, 2021). "It is caused by mutations in the CF transmembrane conductance regulator (CFTR), resulting in multiple complications but especially in the lungs, where there is impaired mucociliary clearance, chronic pulmonary infection and eventual respiratory failure." (PMID 24171060, 2013). "The ion transport abnormalities related to CFTR mutation generate a dehydrated airway surface liquid (ASL) layer, which is responsible for an altered mucociliary clearance, favors infections and persistent inflammation that lead to progressive lung destruction and respiratory failure." (PMID 32982730, 2020). "Unfortunately, CFTR modulator therapy is not effective in all patients, and efficacy varies among patients; it is not a cure, and CF remains a progressive disease that leads predominantly to respiratory failure." (PMID 37511977, 2023).
viral infection (16 papers, 2011 to 2025). "Another interesting explanation of viral impact on CFTR function is the inhibition of its cyclic nucleotidase and cAMP reduction, hence the accession of pathogens and higher prevalence of further viral infections." (PMID 41011750, 2025). "Research indicates its involvement in host defense against viral infections, such as SARS-CoV-2, where CFTR deficiency correlates with decreased susceptibility." (PMID 38892373, 2024). "It had been reported that the CFTR dynamically modulated the intracellular Cl− concentration ([Cl−]i) to regulate host immune defenses and viral infection." (PMID 39205282, 2024). "Given the reduced SARS-CoV-2 infection efficacy observed in KO compared to CFTR WT cells, we tried to dissect the steps of the viral infection likely to be affected by the ablation of CFTR expression." (PMID 38892373, 2024). "Knockdown of CFTR in cells or the inhibition of CFTR activity by pharmacological inhibitors suppressed viral infection and protected mice from HSV-1 and HSV-2 infection." (PMID 39205282, 2024). "With this in mind, we analyzed z-stacked confocal slices of viral infection utilizing 3D volume-rendering software to determine if AAV2 virions colocalized with wild-type CFTR (red) or ΔF508-CFTR (red) in BHK-21 cells." (PMID 21625534, 2011). "Evidence supporting this hypothesis includes studies showing that CFTR hypofunction can be acquired from cigarette smoke exposure, bacterial and viral infections, and neutrophilic inflammation." (PMID 35668512, 2022). "While the RNASEL gene was shown to play a role during Dengue virus infection, MEFV and MASP2 deficiencies may manifest subclinically, and CFTR deficiency leads to severe outcomes that predominantly involve opportunistic bacterial rather than viral infections." (PMID 39062917, 2024). "Using another approach, it has also been proposed that increasing the airway pH in CF individuals by activating CFTR independent HCO3− transport pathways or by inhibiting proton pumps could help prevent or reduce bacterial and viral infections associated with the disease." (PMID 27809281, 2016). "However, since the mechanisms by which viral infections are affected by the respiratory system impairment in pwCF are poorly understood, we believe that the present study may be useful to characterize the impaired process of production and secretion of viral particles in CFTR-modified airway cells." (PMID 36077122, 2022). "As the primary site for virus entry and replication during viral infection, understanding the consequence that lack of CFTR function has on pathophysiology during virus infection is critical for effective disease management." (PMID 30464745, 2018). "It is likely that the correlation between CFTR and ACE-2 is not the only cause for the modulation of the viral infection and that other factors may play a protective role in pwCF infected by SARS-CoV-2." (PMID 37957647, 2023).
Diarrhea (15 papers, 2015 to 2025). Abnormally increased frequency (usually defined as three or more) loose or watery bowel movements a day. "SLC26A3 interacts with several ion transporters linked to intestinal inflammation, such as cystic fibrosis transmembrane conductance regulator (CFTR) and solute carrier family 9 member 3 (SLC9A3) causing congenital sodium diarrhea." (PMID 39992989, 2025). "Accumulated evidences have demonstrated that tannins showed inhibitory effects on enterotoxin-induced secretory diarrheas, which are involved in the hyperactivation of CFTR channel function." (PMID 33676495, 2021). "One such hypothesis theorized that diarrhoea from ErbB SM-TKIs is a form of secretory diarrhoea, activated by apical chloride channels such as calcium-activated chloride channels (CaCC) and cystic fibrosis transmembrane conductance regulator (CFTR)." (PMID 35800225, 2022).
nasal polyps (15 papers, 2011 to 2026). "Using the same antibody as in the present study, frozen sections of excised nasal polyps were shown to express CFTR predominantly in the apical membrane and sub-membranous compartment of ciliated epithelial cells." (PMID 21826241, 2011). "In nasal polyp tissue (upper airways), wt-CFTR was found to be localized at the apical membrane of ciliated cells in areas of differentiated epithelium, while it localized to the cytosol of poorly differentiated areas of the epithelium, similarly to F508del-CFTR in most cell types." (PMID 32365523, 2020). "In the self-paired comparison of the number of cells co-expressed by CFTR and FOXI1 in CRSwNP patients, it was found that the ionocytes that did not express CFTR in the nasal polyps were more common than those in the mucosa." (PMID 36662267, 2023). "GUSB and ATPase plasma membrane Ca2+ transporting 4 (ATP2B4) were identified as reliable genes for normalization of cystic fibrosis transmembrane conductance regulator (CFTR) gene expression in the nasal mucosa and nasal polyps in patients with cystic fibrosis." (PMID 29371606, 2018). "DNA methylation levels were altered not only in NEC, which are directly affected by the disease (CF patients often have rhinitis and nasal polyposis), but also in blood cells where CFTR is not expressed." (PMID 28289476, 2017). "Ionocytes that did not express CFTR was more common in the nasal polyps." (PMID 36662267, 2023). "Second, TGF-β1 inhibits CFTR in epithelial cells from non-CF patients with nasal polyps." (PMID 23671668, 2013).
hereditary pancreatitis (14 papers, 2010 to 2025). "An obstruction with intraductal hypertension may also occur in RAP in patients with CFTR gene mutations, because of the density of pancreatic juice, and in those with hereditary pancreatitis with MPD strictures." (PMID 40217601, 2025). "Pancreatectomy becomes advisable in case of proven idiopathic hereditary pancreatitis and identified mutations in the PRSS1, CFTR, SPINK1, or CTRC genes, especially when there is a risk of ductal adenocarcinoma." (PMID 39896151, 2024). "The major cause of hereditary pancreatitis is the mutation in cationic trypsinogen (PRSS1), serine protease inhibitor Kazal 1 (SPINK1) and cystic fibrosis transmembrane conductance regulator (CFTR) genes." (PMID 32796685, 2020). "Furthermore, more children were diagnosed with hereditary pancreatitis compared to adults (33.3% versus 8%; p < 0.001) and more children reported genetic mutations: PRSS1 mutations (29.2% vs. 6%), SPINK (25% vs. 3%), CFTR mutations (20.9% vs 6.5%) p values of < 0.001, < 0.001 and 0.014 respectively." (PMID 37432930, 2023).
Anxiety (13 papers, 2020 to 2024). Intense feelings of nervousness, tension, or panic often arise in response to interpersonal stresses. "Regression analyses described associations between score changes and age, race, ethnicity, sex, CFTR variant, and prior depression and/or anxiety diagnoses." (PMID 39210645, 2024). "Carrier reporting may leave the family with some anxiety around the possibility of an unrecognised second Cystic Fibrosis Transmembrane Conductance Regulator (CFTR) variant, and clear information is required to minimise this potential harm." (PMID 33073032, 2020). "Another consideration is that there have been cases in adults where doses of CFTR modulators have been reduced in response to side effects, particularly anxiety and neurocognitive effects." (PMID 38397368, 2024). "Although CFTR modulator therapies provide hope for improving clinical outcomes, worsening depression and anxiety occur in some patients when starting these novel agents." (PMID 39408260, 2024). "Given the prolonged life expectancy resulting from novel CFTR modulator therapies, an increased incidence of complications, including psychological issues such as depression and anxiety, is anticipated." (PMID 38136081, 2023). "With anxiety and depression symptoms increasing following the use of CFTR modulator therapies, it is important to consider the continuous implications of health changes." (PMID 35147829, 2022). "Regarding the CFTR-RD risk, the question of the knowledge of the genotype arises: how to decide the benefit/risk balance between the very high sensitivity of the extensive study and the risk of generating undesired genetic data, which may cause anxiety to the patient’s families?" (PMID 33946859, 2021). "Additionally, whilst CFTR modulator therapies provide hope for improving physical health outcomes, several individuals with CF demonstrated worsening depression or anxiety upon commencement of CFTR modulators." (PMID 35147829, 2022). "Also, the rapid and significant change in the wellbeing of CF patients post CFTR modulator therapy, may require patients to make changes to lifestyle and future planning which could potentially contribute to the self-reported anxiety." (PMID 37180712, 2023).
Duchenne muscular dystrophy (13 papers, 2011 to 2024). Duchenne muscular dystrophy (DMD) is a neuromuscular disease characterized by rapidly progressive muscle weakness and wasting due to degeneration of skeletal, smooth and cardiac muscle. "The CRISPR/Cas9 system can also be used as a therapeutic technology for treating genetic disorders such as Duchenne muscular dystrophy (DMD) by correcting the dystrophin gene mutation or cystic fibrosis by repairing the mutation in the CFTR gene." (PMID 27699445, 2017). "This unwanted therapeutic outcome is highlighted in previously published studies in gene replacement studies in Duchenne muscular dystrophy patients and cystic fibrosis transmembrane conductance regulator (CFTR) knock‐out mice." (PMID 33567469, 2021). "Further clinical studies demonstrated the efficacy of aminoglycosides G418 and gentamicin in restoring a significant amount of functional CFTR and dystrophin proteins in CF and Duchenne muscular dystrophy (DMD), respectively." (PMID 32630050, 2020). "These biosensors showed good sensitivity and selectivity against cystic fibrosis transmembrane conductance regulator (CFTR) and Duchenne muscular dystrophy (DMD)." (PMID 36004978, 2022). "In clinical applications, gentamicin was used in CF and DMD (Duchenne muscular dystrophy) patients with restoration of a significant amount of functional CFTR protein or dystrophin." (PMID 31972957, 2020).
bladder cancer (12 papers, 2013 to 2023). "Reasons for a loss of CFTR mRNA expression include promoter hypermethylation as has been reported in lung, breast, head and neck, and bladder cancer studies and somatic CFTR mutations as seen in NSCLC." (PMID 32326161, 2020). "Low CFTR expression in sporadic tumors may also be caused by silencing of the CFTR gene by promoter hypermethylation as was reported in other cancers such as lung, breast, head and neck, and bladder cancers." (PMID 32326161, 2020). "CFTR was also found to be one of the topmost frequently methylated genes in bladder cancer, with aberrant CFTR methylation detected in 55% (73 out of 132) of the cases." (PMID 32365523, 2020). "While CFTR upregulation has been observed in ovarian, cervical, gastric, and nasopharyngeal cancers, hypermethylation and/or downregulation of CFTR were reported in prostate, breast, colorectal, and bladder cancers, non-small cell lung carcinoma (NSCLC), and hepatocellular carcinoma (HCC)." (PMID 32182826, 2020). "A 5-gene panel (VAX1, CFTR, KCNV1, PROX1, and TAL1) had an 88.7% sensitivity and an 87.3% specificity for the diagnosis of bladder cancer." (PMID 37627900, 2023). "CFTR, SAL3, and TWIST1 have been recently shown to be useful for monitoring bladder cancer in a real clinical scenario, as a sensitivity of 96% was achieved by pyrosequencing in combination with urine cytology—however with low specificity (40%)." (PMID 32046186, 2020). "Accordingly, methylation profiling of urine sediments, to detect the top four frequently methylated genes, namely SALL3, CFTR, ABCC6, and HPP1, together can detect bladder cancer with 82.6% sensitivity and 100% specificity." (PMID 30901947, 2019).
cholestasis (12 papers, 2015 to 2026). Impairment of the bile flow caused by obstruction within the liver, or outside the liver in the bile duct system. "Both genetic and phenotypic features of this subtype of cholestasis related to CFTR-RD variants appear to be different from the classical chronic liver diseases associated with CF." (PMID 35626323, 2022). "Our work raises the hypothesis of a specific cholestasis entity associated with mutations in CFTR, different from chronic liver disease associated with CF." (PMID 35626323, 2022). "In addition, mutations in cholangiocyte transporter genes (e.g., the cystic fibrosis transmembrane conductance regulator (CFTR) gene) can cause cholestasis." (PMID 35740260, 2022). "In the liver, CFTR is expressed at the apical membrane of cholangiocytes within the bile ducts and defective CFTR results in impaired biliary secretion and ductal cholestasis." (PMID 30893953, 2019). "Apart from a CFTR (NM_000492) heterozygous known pathogenic variant, c.3209G > A (p.R1070Q), was identified in P4, no additional pathogenic variant was identified in other cholestasis causing genes." (PMID 35534800, 2022).
pulmonary fibrosis (12 papers, 2005 to 2025). Chronic progressive interstitial lung disorder characterized by the replacement of the lung tissue by connective tissue, leading to progressive dyspnea, respiratory failure, or right heart failure. "To gain insight into the mechanism underlying SphK2-mediated pulmonary fibrosis under chronic CS exposure, we investigated the CFTR expression in lung tissues from both WT and SphK2−/− mice in response to CS exposure." (PMID 36226596, 2023). "In contrast, inhibition of S1P signaling with the S1P receptor analogue FTY720 rescued CFTR expression, suppressed Nf-κB-p65 expression and nuclear translocation, and alleviated pulmonary fibrosis and inflammation after CS exposure." (PMID 36226596, 2023). "Furthermore, the downstream protein-coding gene, STX16, is shown to interact with the N-terminal region of CFTR (cystic fibrosis transmembrane conductance regulator) in epithelial cells, suggesting a possible relation to pulmonary fibrosis." (PMID 35202087, 2022).
Renal cyst (12 papers, 2010 to 2025). A fluid filled sac in the kidney. "The activation of AMPK is known to inhibit CFTR-mediated chloride secretion and mTOR-mediated cell proliferation, which are two underlying mechanisms of renal cyst growth." (PMID 33261193, 2020). "The role of CFTR-dependent Cl− secretion for growth of renal cysts has been implicated for long." (PMID 32185407, 2020). "Mouse studies have suggested pharmacological inhibition of CFTR, CFTR corrector, or genetic inactivation of Tmem16a chloride channels can slow renal cyst enlargement." (PMID 41122971, 2025). "It is characterized by the development and enlargement of renal cysts due to increased cell proliferation, extracellular matrix abnormalities, and increased CFTR-mediated transepithelial fluid secretion." (PMID 37686084, 2023). "Previous studies reveal that nuclear receptors, including peroxisome proliferator–activated receptor gamma (PPARγ) and liver X receptor (LXR), inhibit CFTR-mediated chloride secretion and lead to a decrease in renal cyst progression." (PMID 35457146, 2022). "The present study revealed the pharmacological effects of panduratin A and their corresponding mechanisms on CFTR-mediated chloride secretion and renal cyst enlargement using Madin–Darby canine kidney (MDCK) cell–derived cysts." (PMID 35457146, 2022). "Here we investigated the pharmacological effects of panduratin A, a bioactive compound known as an AMPK activator, on CFTR-mediated chloride secretion and renal cyst development using in vitro and animal models of PKD." (PMID 35457146, 2022). "The data suggest that both Ca2+-activated TMEM16A and cAMP-dependent CFTR Cl− channels contribute to renal cyst development." (PMID 32185407, 2020). "Remarkably, enhanced expression of CFTR in cystic kidneys is entirely reversible upon additional knockout of Tmem16a in Pkd1−/−/T16a−/− animals." (PMID 32859916, 2020). "An overall decrease in CFTR labeling was also observed in the immuno-gold labeled EM of renal cyst sections taken from animals treated with pioglitazone for 14 weeks." (PMID 21052534, 2010). "Additionally, other ion channels, such as TMEM16A and CFTR, were identified as key players in fluid secretion into renal cysts during in vitro studies." (PMID 40136708, 2025). "Importantly, 5′ AMP-activated protein kinase (AMPK) activation by metformin, an anti-diabetic drug, was found to reduce renal cyst formation and growth through the inhibition of cell proliferation and CFTR-mediated fluid secretion." (PMID 35457146, 2022). "However, the lower abundance of CFTR expression in the renal cysts from both the treated and untreated animals precluded a statistical assessment for an alteration of CFTR immunoreactivity in the apical membrane." (PMID 21052534, 2010). "Accumulating evidence suggests that AMPK activation (using metformin, salsalate, 2-deoxyglucose, or diet) may restore mitochondrial function and slow cystogenesis by inhibiting mTORC1 and the cystic fibrosis transmembrane conductance regulator (CFTR) in the cystic kidney." (PMID 39000280, 2024). "Therefore, the inhibitory effect of panduratin A on cell proliferation and CFTR-mediated fluid secretion might retard renal cyst progression in PKD." (PMID 35457146, 2022). "Support for a pro-secretory role of CFTR in ADPKD came from a number of in vitro studies, ex vivo experiments in embryonic renal cysts in metanephric organ culture, and observations in vivo in animals and humans." (PMID 34199520, 2021). "Apart from the differences in TMEM16A-expression, CFTR might be expressed at lower levels in female ADPKD individuals, which could contribute to reduced renal cyst growth in females." (PMID 34199520, 2021).